TSC2 (TSC complex subunit 2)
Diseases named in the same sentence as TSC2 in open-access papers (continued):
Sharing a sentence is not in itself a finding about the gene and the disease.
cystadenoma (6 papers, 2007 to 2023). A benign or borderline cystic epithelial neoplasm arising from the glandular epithelium. "In this work, MRI was shown to be an efficient modality for robustly identifying cysts as well as cystadenomas in 6-7-month-old Tsc2+/- mice." (PMID 35814396, 2022). "In the present study, we identified clear cystadenoma on the surface of most kidneys derived from Tsc2+/− mice at the age of 1 year, along with prominent epithelial cell proliferation." (PMID 29491408, 2018). "In A/J Tsc2+/- mice, cystadenoma score per kidney in untreated animals at 9 months of age is 74.4, and cystadenoma score per kidney is 41.13 in the groups treated daily × 4 weeks, but 21.50 in the group treated daily × 4 weeks then weekly × 8 weeks." (PMID 20146790, 2010). "All three treatment cohorts showed a significant decrease in the average cystadenoma score per kidney as compared to both the 9 month and 12 month A/J Tsc2+/- untreated control groups (number of cystadenomas gave similar trends)." (PMID 20146790, 2010). "In the Tsc2+/- study reported here, we observed that the combination treatment cohort had a lower cystadenoma score than the single-agent CCI-779 cohort in both the 6–8 month and 10–12 month groups, although this difference was not statistically significant." (PMID 17986349, 2007). "Although we refer to all Tsc2+/- mouse kidney lesions collectively as cystadenomas, they can be subdivided into 3 subtypes: cystic lesions, papillary lesions, and solid tumors." (PMID 17986349, 2007). "It is possible that a more potent AMPK activator such as AICAR or phenformin would be more effective at inhibition of both mTORC1 signaling and growth in Tsc2+/− cystadenoma lesions since they are also more effective in in vitro studies on TSC2-deficient fibroblasts." (PMID 22363765, 2012). "We suspect that the complete absence of Tsc2 in these Tsc2+/− cystadenoma lesions leads to strong activation of mTORC1 due to constitutive high levels of RHEB-GTP, which makes these lesions resistant to the lesser effect of Raptor phosphorylation." (PMID 22363765, 2012).
endometrial cancer (6 papers, 2011 to 2024). Primary or metastatic malignant neoplasm involving the endometrium (mucous membrane that lines the endometrial cavity). "Increased expression and activity of mTOR kinase in endometrial cancer has been connected with the loss of PTEN, LKB1 (Liver Kinase B1) and TSC2 activity as well as increased expression of Phospholipase D1." (PMID 22920721, 2012). "While pTEN alterations are well known in endometrial cancer, signaling defects involving the downstream effector mTor, or other tumor suppressors that regulate mTor signaling, including TSC2 and LKB1, are less documented." (PMID 21931726, 2011).
lung disease (6 papers, 2016 to 2025). "Our mouse lung-mesenchymal Tsc2-null model will be useful in understanding the evolution of mTORC1-driven lung pathologies and will serve as a preclinical model for identifying and testing therapeutic targets, not only for LAM but also potentially for other lung diseases with activated mTORC1." (PMID 33159078, 2020).
rhabdomyoma (6 papers, 2014 to 2024). A benign mesenchymal tumor arising from skeletal or cardiac muscle. "Analysis of disease trajectories revealed a more diverse clinical outcome for TSC2 patients: however, a chronological association of rhabdomyoma, NDD and KD was most frequently observed for TSC1 patients." (PMID 35440050, 2022). "Tuberous sclerosis complex (TSC), caused by autosomal dominant mutations in either TSC1 or TSC2 that causes a plethora of cellular dysfunctions due to mTOR inhibition, has heart symptoms in the form of rhabdomyomas in addition to other organ involvements such as the skin and brain." (PMID 39241028, 2024). "Of the cases studied herein, only one case [ET200, with a novel PV in TSC2 (c.1258–2A>G)] had prenatal detection of rhabdomyoma; however, the presence of hypomelanotic macules at neonatal age allowed for a definitive diagnosis of TSC." (PMID 32313033, 2020). "Intracardiac tumour (rhabdomyoma), neurodevelopmental disorders (NDDs) and kidney disorders (KD) are common manifestations of TSC and have been linked with TSC1 and TSC2 loss-of-function mutations independently, but the dynamic relationship between these organ manifestations remains unexplored." (PMID 35440050, 2022). "The location of rhabdomyoma within the heart was also compared between TSC1 and TSC2 patients to evaluate whether their genotype impacted the preferential location CR development within different heart structures." (PMID 35440050, 2022).
cervical carcinoma (5 papers, 2007 to 2023). A carcinoma arising from either the exocervical squamous epithelium or the endocervical glandular epithelium. "CRKL depletion significantly alters the retention of variable introns of PTK2B and TSC2, and the inclusion of variable exons of MELK, and these tumorigenesis involving genes might then affect development or progression of cervical carcinoma." (PMID 31133010, 2019).
diabetes (5 papers, 2014 to 2024). "The use of different strategies affecting these signaling pathways, such as GK activators or a preserved TSC2 activity, could be beneficial for the maintenance of pancreatic β cells for longer periods of time, avoiding its loss in pathologies such as type 2 diabetes mellitus." (PMID 31583121, 2019). "This study proves that TSC2 in its deacetylated form is essential for regulating mTORC1 signalling and the maintenance of the mitochondrial quality control, which is involved in the homeostasis of pancreatic beta cells and prevents from several metabolic disorders such as Type 2 Diabetes Mellitus." (PMID 38822085, 2024).
Dravet syndrome (5 papers, 2020 to 2025). "Preferred adjunctive applications of the KD include genetic epilepsies, such as SCN1A-related Dravet syndrome, TSC1/TSC2-related tuberous sclerosis complex, and UBE3A-related Angelman syndrome." (PMID 40290041, 2025).
gastric cancer (5 papers, 2016 to 2023). A primary or metastatic malignant neoplasm involving the stomach. "One TSC2 missense mutation (p.E588K) was found in a gastric cancer patient." (PMID 26859683, 2016).
Glucose intolerance (5 papers, 2021 to 2025). Glucose intolerance (GI) can be defined as dysglycemia that comprises both prediabetes and diabetes. "IPA suggested four upstream regulators that could be linked to glucose intolerance: interleukin 6 (IL6), tuberous sclerosis complex 2 (Tsc2), peroxisome proliferator-activated receptor gamma coactivator 1-beta (Ppargc1b), and lysine (K)-specific histone demethylase 1A (Kdm1a)." (PMID 35377872, 2022). "In contrast, the TSC2-KOPlacenta mice appear to have increased insulin sensitivity without glucose intolerance." (PMID 34032632, 2021). "The lack of glucose intolerance after chronic elevation of glucagon in αRhebTg mice and the reduced responses to glucagon administration recapitulate the glucagon resistance phenotype observed in mice with constitutive hyperglucagonemia by constitutive deletion of TSC2 in α cells." (PMID 37140984, 2023).
hepatic angiomyolipoma (5 papers, 2016 to 2025). An angiomyolipoma arising from the liver. "Our data, in line with previous studies, indicate that in TSC patients there is an age-related LAM prevalence, a higher frequency of TSC2 mutations (statistically borderline in our study), and more frequent occurrence of renal and hepatic angiomyolipomas." (PMID 27171001, 2016). "The median age at surgery was 11 years (IQR: 1.55–15.5), and the indications for surgery included HB (n = 1), HCC (n = 1), hepatic angiomyolipoma associated with a TSC-2 mutation (n = 1), large β-catenin mutated hepatic adenoma (n = 1), and hepatic mesenchymal hamartoma (n = 1)." (PMID 40182007, 2025). "The most common liver lesions in TSC patients are hepatic angiomyolipoma which are benign tumors consisting of smooth muscle cells, fibrous tissue, adipose tissue, and abnormally formed vascular channels and are more common in patients with TSC2 mutations, commonly occurs in adults." (PMID 41238564, 2025). "A recent retrospective analysis found that among 25 patients with liver PEComa, 88% also had renal AML, and TSC2 patients had a higher prevalence of liver PEComa than TSC1 patients (18% vs 5%; P = 0.037)." (PMID 39026968, 2024).
lung adenocarcinoma (5 papers, 2019 to 2026). A carcinoma that arises from the lung and is characterized by the presence of malignant glandular epithelial cells. "Alterations in TSC2 have been identified in 3.39% of all cancers, with a higher prevalence in lung adenocarcinoma, colon adenocarcinoma, breast invasive ductal carcinoma, endometrial endometrioid adenocarcinoma, and high-grade ovarian serous adenocarcinoma." (PMID 41522204, 2026). "Specifically mentioned here that, in addition to identifying two mutations in TSC2, CMA detected complex genomic abnormalities involving multiple chromosomes in patient ID052 with concurrent diagnosis of lung adenocarcinoma." (PMID 31856217, 2019). "The relative transcript level of ERα (ESR1) was significantly higher in 621–101 cells (CT = 30.7) relative to lung adenocarcinoma A549 cells (CT = 36.4) (p < 0.001), although TSC2-reexpression (621–103 cells) did not affect ESR1 expression." (PMID 32078667, 2020).
non-small cell lung carcinoma (5 papers, 2014 to 2022). A group of at least three distinct histological types of lung cancer, including non-small cell squamous cell carcinoma, adenocarcinoma, and large cell carcinoma. "We correlated the expression of hamartin, p-TSC2 and p-mTOR with expression data concerning epidermal growth factor receptor mutations in non-small cell lung cancer and their influence on downstream Akt, MAPK and Stat3 signaling." (PMID 24593867, 2014). "Phosphorylation of at least two of the three further known Akt target proteins Proline-rich AKT1 substrate 1 (PRAS40), tuberous sclerosis 2 (TSC2) and TBC1 Domain Family Member 4 (TBC1D4) in non-small cell lung cancer cell lines also required Akt1-phosphorylation at T308 for their activation." (PMID 29562639, 2018). "In a study of non-small cell lung cancer, it was found that p-Akt(Thr308), but not p-Akt(Ser43) correlated with phosphorylation of three downstream substrates (PRAS40, TSC2, and TBC1D4), leading the authors to suggest that p-Akt(Thr308) represents a better measure of Akt activity in these tumors." (PMID 26793165, 2015).
sarcoidosis (5 papers, 2020 to 2025). Sarcoidosis is a multisystemic disorder of unknown cause characterized by the formation of immune granulomas in involved organs. "In mice, we previously showed that chronic activation of mTORC1 by deletion of its negative regulator Tsc2 in macrophages alone leads to spontaneous development of a granulomatous phenotype in lungs and skin that resembles sarcoidosis." (PMID 38353578, 2024). "Human skin biopsies from sarcoidosis patients and a myeloid Tsc2-specific sarcoidosis mouse model were analyzed for validatory experiments." (PMID 38353578, 2024). "The most promising experimental models include mice with TSC2 deletion and an in silico multiscale computational model of sarcoidosis (SarcoidSim), developed using transcriptomics and flow cytometry of human sarcoid biopsies." (PMID 37511027, 2023). "It is reasonable to conclude based on available evidence that the murine Tsc2 knockout model identifies an important immunological pathway that contributes to sarcoidosis disease progression." (PMID 32849608, 2020). "A serendipitous link to human sarcoidosis granuloma formation was recently discovered based on a murine Tsc2 knockout model." (PMID 32849608, 2020). "While these findings are significant—particularly given the role of mTOR and autophagy in the pathogenesis of sarcoidosis— available genome-wide association studies (GWAS) have not identified TSC2 mutations as a risk factor for sarcoidosis." (PMID 39996765, 2025). "However, genome wide association studies have not identified variations of the Tsc2 gene as a risk factor for sarcoidosis, and the upstream regulators of mTORc1 in humans with sarcoidosis are unknown." (PMID 32849608, 2020).
Seizure (5 papers, 2020 to 2026). A seizure is an intermittent abnormality of nervous system physiology characterized by a transient occurrence of signs and/or symptoms due to abnormal excessive or synchronous neuronal activity in the brain. "Overall, our data indicated that Tsc2+/− present higher susceptibility to KA‐induced seizures than their WT littermates, which differ in a sex‐ and circadian cycle‐dependent manner." (PMID 39010669, 2024). "Our work demonstrated for the first time the susceptibility of the TSC2 mouse model to KA‐induced seizures and disclosed the effects of sex and the circadian cycle." (PMID 39010669, 2024).
Tinnitus (5 papers, 2022 to 2025). Tinnitus is an auditory perception that can be described as the experience of sound, in the ear or in the head, in the absence of external acoustic stimulation. "A whole exome sequencing study of severe tinnitus reported an enrichment of rare missense variants in several synaptic genes, including ANK2, AKAP9 and TSC2, in a Spanish cohort of Meniere’s Disease (MD) patients with catastrophic tinnitus (N=59)." (PMID 41378354, 2025). "Previous research revealed the presence of genes related with axonal branching (ANK2, AKAP9, and TSC2) in tinnitus patients." (PMID 38562529, 2024). "In Spanish patients with MD, using exome sequencing and gene burden analyses, severe tinnitus has been associated with rare missense variants in 24 synaptic genes, including ANK2, TSC2, and AKAP9." (PMID 38254912, 2023). "Individuals with missense variants in known genes described for severe tinnitus such as ANK2, TSC2, and AKAP9 were targeted for specific LSVs overlapping these genes." (PMID 36450758, 2022). "We also found some rare variants previously reported in genes associated with tinnitus such as ANK2, AKAP9 and TSC2." (PMID 36450758, 2022). "Moreover, gene burden analyses in sequencing data from Spanish and Swede patients with severe tinnitus have identified and replicated ANK2, AKAP9, and TSC2 genes." (PMID 38334885, 2024). "Although several rare missense SNVs were reported in MD and severe tinnitus, including ANK2, TSC2, and AKAP9 genes, these variants do not explain the presence of other comorbidities with a higher prevalence." (PMID 38254912, 2023).
tumor syndrome (5 papers, 2008 to 2024). "TSC1 and TSC2 are the tumor-suppressor genes mutated in the tumor syndrome TSC (tuberous sclerosis complex) and their gene products form a complex (TSC1–TSC2) that integrates signals upstream of mTOR signaling pathway through its GAP activity towards the small G-protein Rheb." (PMID 23977024, 2013).
type 2 diabetes (5 papers, 2012 to 2024). "The Tsc2 gene product has a more direct effect on mTORC1, and less oncogenic potential that AKT, and by corroborating such results we will obtain valuable information to develop new therapeutic strategies for the control and treatment of type 2 diabetes." (PMID 24893199, 2012). "In summary, resveratrol facilitates TSC2 recruitment to the lysosome, inhibiting mTORC1 pathway and improving the mitochondrial turnover, contributing to pancreatic β cell homeostasis in a TSC2 and SIRT-1 dependent manner, which is crucial in avoiding metabolic disorders such as type 2 diabetes." (PMID 38822085, 2024).
acute myeloid leukemia (4 papers, 2022 to 2026). Acute myeloid leukemia (AML) is a group of neoplasms arising from precursor cells committed to the myeloid cell-line differentiation. "In a study on acute myeloid leukemia (AML) cells, the results of genome-wide CRISPR/Cas9 screens revealed negative regulators of the MAPK and mTORC1 signaling pathways, including LZTR1, NF1, and TSC1 or TSC2, were associated with sorafenib resistance." (PMID 35715750, 2022).
adenoma (4 papers, 2012 to 2022). A neoplasm arising from the epithelium. "TSC2 loss was detected in five patients; since it is a tumor suppressor gene, we assume that its absence is involved in adenoma formation." (PMID 35887000, 2022). "We have shown that defective LKB1/TSC1/TSC2/mTORC1 signaling in mesenchymal cells is sufficient to cause epithelial hyperplasia, adenoma and paratubal cysts in oviducts, and uterine endometrial cancer in mice." (PMID 22916036, 2012). "TSC1 and TSC2 are growth suppressor genes, therefore, we conclude that loss of TSC2 could contribute to adenoma development." (PMID 35887000, 2022).
Alzheimer disease (4 papers, 2013 to 2025). A progressive, neurodegenerative disease characterized by loss of function and death of nerve cells in several areas of the brain leading to loss of cognitive function such as memory and language. "In addition, we found 5 probes that were correlated with cognitive function including two probes in the TSC2 gene that has previously been associated with Alzheimer’s disease pathology." (PMID 24373378, 2013). "In Alzheimer's disease, TSC1 aggregates form in the absence of TSC2 in the CA1 region of the hippocampus, leading to increased inflammation, altered autophagy, β‐amyloid accumulation and cell death via mTOR." (PMID 39962362, 2025).
Cowden syndrome (4 papers, 2008 to 2023). "Peutz-Jeghers syndrome is caused by mutations in LKB, an upstream regulator of AMPK and TSC2, and Cowden’s syndrome is caused by mutations in PTEN that also activate mTORC1." (PMID 24092877, 2014). "Interestingly, BHD is a member of the hamartoma syndrome family that includes Cowden syndrome (CD, affected gene PTEN), Peutz-Jeghers syndrome (PJS, affected gene LKB1), and tuberous sclerosis complex (affected genes TSC1/TSC2)." (PMID 18974783, 2008). "As one of the hamartoma syndromes, BHD shares many clinical features (such as follicular hamartomas, mucosal fibromas, and internal malignancy) with Cowden syndrome (CD, affected gene PTEN), Peutz-Jeghers syndrome (PJS, affected gene LKB1), and tuberous sclerosis complex (affected genes TSC1/TSC2)." (PMID 18974783, 2008).
Focal cortical dysplasia (4 papers, 2018 to 2025). A type of malformation of cortical development that primarily affects areas of neocortex. "Focal cortical dysplasias (FCDs) are localized MCDs, formerly believed to mostly result from a toxic insult to the developing brain, but recently also associated with DEPDC5 mutations and somatic mutations in MTOR, PIK3CA, AKT3, PTEN, TSC1 and TSC2." (PMID 35323703, 2022).
Hypertension (4 papers, 2021 to 2023). The presence of chronic increased pressure in the systemic arterial system. "Only the individual with the TSC2/PKD1 deletion was diagnosed with hypertension and decreased kidney function." (PMID 37386496, 2023). "Patients with TSC2-polycystic kidney disease 1 deletion syndrome and hypertension treated with ACE inhibitors or angiotensin receptor blockers had decreased renal AML development compared to control." (PMID 36220392, 2022). "Furthermore, patients with TSC2-polycystic kidney disease 1 deletion syndrome and hypertension treated with inhibition of the RAS pathway via angiotensin receptor blockade had decreased renal AML development compared to those who did not receive this therapy." (PMID 36220392, 2022). "Secondly, the study population was small and heterogeneous in terms of age, presence of arterial hypertension, the extent of renal involvement, genetic background (TSC1, TSC2, TSC2+PKD1), and treatment with mTOR inhibitors." (PMID 34912759, 2021).